PRKCE (protein kinase C epsilon)
Diseases named in the same sentence as PRKCE in open-access papers (continued):
Sharing a sentence is not in itself a finding about the gene and the disease.
tumor (14 papers, 2013 to 2025). "An in-depth study of the expression, prognosis, and mechanism of PRKCE decreased expression and the association of PRKCE with tumor immune infiltration in KIRC can further reveal the cause of immunotherapy unresponsiveness and provide clues for KIRC immunotherapy." (PMID 36186442, 2022). "In PC cells, PKM2 phosphorylation upon interaction with protein kinase C epsilon (PKCε) enhances its nuclear translocation, leading to the upregulation of oncogenes and the promotion of tumor proliferation." (PMID 41169372, 2025). "Our study found the important role of PRKCE in KIRC and provided an underlying mechanism of PRKCE decreased expression and a potential relationship with tumor-immune infiltrations." (PMID 36186442, 2022). "TISIDB database analysis demonstrated that decreased expression of PRKCE was most correlated with tumor grade and stage in KIRC." (PMID 36186442, 2022). "Overexpression of protein kinase C epsilon (PRKCE), a phorbol ester receptor, is a hallmark of multiple cancers and has been widely implicated in malignant transformation, tumor aggressiveness, and metastasis." (PMID 36362284, 2022). "The results showed that expression levels of PRKCE in 531 tumor tissues were lower than in 100 normal samples (p < 0.001)." (PMID 36186442, 2022). "The Spearman correlation analysis quantified by ssGSEA has been applied to demonstrate the association between the immune cell infiltration level and expression level (TPM) of PRKCE to assess the effect of PRKCE on the tumor microenvironment (TME)." (PMID 36186442, 2022). "LinkedOmics integrated analysis demonstrated a significantly inversely relationship of PRKCE DNA methylation in Illumina 450K array and 27K array with PRKCE transcriptional expression and were significantly related to tumor stage in KIRC patients." (PMID 36186442, 2022). "In this study, we investigated the correlation between decreased expression of PRKCE and tumor-infiltration immune cells." (PMID 36186442, 2022). "PRKCE is known to be implicated in EMT by which it mediates the motility of cells and tumor invasion." (PMID 33931671, 2021). "Matched to other genes, PRKCA, PRKCB, and PRKCE were more involved in many normal tissue mRNA profiles than tumor ones." (PMID 35174160, 2021). "Collectively, miR-205-5p negatively regulated the PRKCE and enhanced gemcitabine-induced apoptosis and tumor growth in vivo." (PMID 32869841, 2020). "In one tumor with MNA and its associated cell line, a few novel amplicons were found, which encompassed genes such as GDF7, FSHR, PRKCE, and TMEM18." (PMID 23656755, 2013). "We found that PRKCE decreased in KIRC tumor tissue compared to normal tissue." (PMID 36186442, 2022). "Inconsistent to our study, the results from the tumor xenograft mouse model provided evidence that miR-218-5p enhanced gemcitabine-induced apoptosis and GBC chemosensitivity by targeting PRKCE." (PMID 32869841, 2020). "We analyzed PRKCE expression in our 36 pairs of CNG and GBC tumor samples, and found an increased expression in GBC." (PMID 28492560, 2017). "Taken together, our study demonstrated that miR-218-5p is a potent tumor chemoresistance suppressor in the GBC and that its chemosensitization effects are mediated, at least in part, via downregulation of the PRKCE/MDR1 pathway." (PMID 28492560, 2017). "miR-205 has been shown to be epigenetically repressed tumor suppressor in PCa that exerts its tumor-suppressive functions in the human prostate through down-regulation of multiple targets such as BCL2, protein kinase C epsilon and androgen receptor (AR)." (PMID 24167554, 2013). "The prognostic value and the potential mechanism of PRKCE aberrant expression in KIRC remain not fully investigated, although PKC epsilon (ε) was upregulated in KIRC and was associated with tumor Fuhrman grade and T stage in clear cell RCCs." (PMID 36186442, 2022). "We, therefore, speculated that the PRKCE and miR-205-5p may function in GBC through tumor stem cells." (PMID 32869841, 2020).
tumor (continued). "Indeed, downregulation of PRKCE expression reduced IC50 of gemcitabine and increased tumor-killing effect of gemcitabine in NOZ and GBC-SD cells." (PMID 28492560, 2017). "Moreover, PRKCE expression was significantly negatively correlated with the infiltration of macrophages, CD8+ T cells, Tregs, and MDSC, but not with tumor purity by TIMER2.0 analysis." (PMID 36186442, 2022).
infection (4 papers, 2017 to 2023). The state of being infected such as from the introduction of a foreign agent such as serum, vaccine, antigenic substance or organism. "For example, TNFSF13B, FOS, POLR3G and PRKCE were down-regulated at 3 h post infection, while ITGB7 and THBD were up-regulated." (PMID 28938587, 2017). "We propose that our results convincingly suggest that circ_3205 is a circRNA synthesized by SARS-CoV-2 upon host cell infection and that it may behave as a competitive endogenous RNA (ceRNA), sponging hsa-miR-298 and contributing to the upregulation of KCNMB4 and PRKCE mRNAs." (PMID 35039944, 2022).
adenocarcinoma (1 paper, 2015). A common cancer characterized by the presence of malignant glandular cells. "For adenocarcinoma specifically, DM was observed in promoters [hypermethylated RASL12; SPTAN1, mir-26a, hypomethylated NQO1, SIRPB1, NF1A] and gene bodies [hypermethylated AKAP13, ANK family, PRKCE, ROS1; hypomethylated FAM171A1, PARK2, BCAS3, RHOJ] and many others." (PMID 26683690, 2015).
cardiovascular disease (1 paper, 2018). "Analysis of the interactome and disease-related network on the 44-dysregulated genes identified HDAC9, SMAD4, PTGFR, and PRKCE as the highest scoring genes within the cardiovascular disease category." (PMID 29520069, 2018).
peripheral neuropathy (1 paper, 2023). A disorder affecting the peripheral nervous system. "Lastly, we elucidated that the intracellular signalling pathways, phospholipase C (PLC) and protein kinase C epsilon (PKCε), downstream from kinin B2 receptor activation are critical to sensitising the TRPA1 channel in the cisplatin-induced peripheral neuropathy model in mice." (PMID 37513871, 2023).
psychiatric disorder (1 paper, 2013). A disorder characterized by behavioral and/or psychological abnormalities, often accompanied by physical symptoms. "PRKCE interacts with several proteins encoded by genes of potential relevance to psychiatric disorders, including the glutamate decarboxylases (GAD1, GAD2), NMDA receptors (GRIN2D, GRIN1), and a metabotropic glutamate receptor (GRM5)." (PMID 23922650, 2013).
PRKCE also shares sentences with these, for which no sentence is quoted: acute myeloid leukemia (2 papers); alcoholic neuropathy (1); Alzheimer disease (1); brain tumors (1); Cerebral ischemia (1); Cirrhosis (1); colon cancer (1); diabetic neuropathy (1); hepatocellular carcinoma (1); Huntington disease (1); Hyperglycemia (1); lung squamous cell carcinoma (1); myonecrosis (1); neuroblastoma (1); non-Hodgkin lymphoma (1); non-small cell lung carcinoma (1); Nonalcoholic fatty liver disease (1); pancreatic cancer (1); SARS-CoV infection (1); skin cancer (1); tongue SCC (1).